PEG13 (paternally expressed 13)
Gene: Long non-coding RNA gene on chromosome 8 (140,092,781 to 140,100,553, reverse strand). Ensembl gene ENSG00000282164.
Diseases named in the same sentence as PEG13 in open-access papers:
PEG13 is named in the same sentence as 5 diseases in open-access papers, as found by Europe PMC text mining. Sharing a sentence is not in itself a finding about the gene and the disease. The quoted sentences say what the papers report.
epilepsy (2 papers, 2023 to 2025). A brain disorder characterized by episodes of abnormally increased neuronal discharge resulting in transient episodes of sensory or motor neurological dysfunction, or psychic dysfunction. "Experimental evidence from rodent epilepsy models reveals that hippocampal Psmd11 expression undergoes coordinated regulation through lncRNA Peg13-mediated molecular interactions." (PMID 40791576, 2025). "The resultant suppression of epileptogenic processes highlights the Peg13/miR-490-3p/Psmd11 axis as both a disease-promoting network and a viable therapeutic target for seizure disorders." (PMID 40791576, 2025). "The expression of PSMD11 was down-regulated in the hippocampus of epileptic mice, and the lncRNA Peg13 was shown to up-regulate PSMD11 in a miR-490-3p-dependent manner, thereby inactivating the Wnt/β-catenin pathway and relieving epilepsy progression in mice." (PMID 37349676, 2023).
Sepsis (1 paper, 2024). Sepsis is defined as life-threatening organ dysfunction caused by a dysregulated host response to infection. "To investigate the role of Peg13 in modulating the inflammatory response in sepsis, we established Lipopolysaccharide (LPS)-induced 293T cells and mouse models." (PMID 38856110, 2024). "Peg13 mitigates the inflammatory response by reducing the release of proinflammatory cytokines HMGB1 and IL-6 in sepsis, presenting a potential therapeutic target for alleviating inflammation in sepsis treatment." (PMID 38856110, 2024).
infection (2 papers, 2020 to 2024). The state of being infected such as from the introduction of a foreign agent such as serum, vaccine, antigenic substance or organism. "Peg13 expression was assessed at various time points after infection using RT-qPCR." (PMID 38856110, 2024).
cancer (1 paper, 2022). A tumor composed of atypical neoplastic, often pleomorphic cells that invade other tissues. "In addition, other genes found dysregulated in our cell models (in common in A549 and SH-SY5Y cells) are H19 and PEG13, both imprinted genes whose product is a long-noncoding RNA, display differences in methylation with dysregulated patterns of imprinting in several cancers." (PMID 35163690, 2022).
neurodevelopmental disorder (1 paper, 2022). A behavioral and cognitive disorder with onset during the developmental period that involves impaired or aberrant development of intellectual, motor, or social functions. "The Peg13 imprinting cluster is associated with neurodevelopmental disorders and comprises canonical imprinted genes, which are conserved between mouse and human, as well as brain-specific imprinted genes in mouse." (PMID 36313557, 2022).